MCL1 (MCL1 apoptosis regulator, BCL2 family member)
Diseases named in the same sentence as MCL1 in open-access papers (continued):
Sharing a sentence is not in itself a finding about the gene and the disease.
gastric cancer (continued). "Here, we investigated the relationship between the anticancer effect of Genipin and signal transducer and activator of transcription (Stat3)/myeloid cell leukemia-1 (Mcl-1) in human gastric cancers." (PMID 31351462, 2019). "Many targets of miR-29a have been identified, such as VEGF in gastric carcinoma and MCL1 in anaplastic large cell lymphomas." (PMID 31885817, 2019). "Further studies have reported the miR-101 induces MCL1 silencing in gastric cancer, NSCLC, endometrial cancer, and triple negative breast cancer (TNBC)." (PMID 29361709, 2018). "Taken together, our findings broaden the view of PI3K/Akt pathway as an important regulator in Taxol acquired resistance, and implicate Mcl-1 as a specific therapeutic target for the treatment of Taxol-resistant human gastric cancer." (PMID 29137317, 2017). "Extracellular HMGB1 can protect gastric cancer cells from apoptosis induced by vincristine via transcriptional up-regulation of myeloid cell leukemia-1 (Mcl-1, an anti-apoptotic member of the Bcl-2 protein family)." (PMID 28969092, 2017). "Knockdown of MCL-1 also enhances sensitivity to cisplatin in gastric cancer cells expressing high levels of MCL-1." (PMID 28659182, 2017). "Further, we find that the enhanced Mcl-1 prevents of the permeabilization of the outer mitochondrial membrane, and identifies Mcl-1 as a potential therapeutic target for the treatment of Taxol-resistant human gastric cancer." (PMID 29137317, 2017). "Inhibition of Mcl-1 or PI3K/Akt pathway significantly reversed the resistant phenotype of Taxol-resistant human gastric cancer cells." (PMID 29137317, 2017). "Mcl-1 is shown to be stabilized in Taxol -resistant gastric cancer cells because of the hyper-activation of the PI3K/Akt signaling pathway." (PMID 29137317, 2017). "Here we report that upregulation of Mcl-1 (Myeloid cell leukemia-1) confers acquired resistance to Taxol in human gastric cancer." (PMID 29137317, 2017). "Taken together, these results strongly suggest the critical role of Mcl-1 in the acquired resistance to Taxol in human gastric cancer cells." (PMID 29137317, 2017). "Mcl-1 is highly upregulated in Taxol-resistant human gastric cancer cells and the up-regulation of Mcl-1 confers the resistance of gastric cancer cells to Taxol." (PMID 29137317, 2017). "Increased expression of miR-29c induced apoptosis in gastric cancer cells via suppression of oncogene Mcl-1." (PMID 28427151, 2017). "Collectively, these data suggest that Mcl-1 stabilization response to PI3K/Ak pathway plays an important role in the development of Taxol resistance in human gastric cancer cells." (PMID 29137317, 2017). "Mature miR-512-5p is encoded by the intergenic miR-512-1 and miR-512-2 genes located on human chromosome 19 and was reported to suppress apoptosis by targeting MCL-1 in gastric cancer and hTERT in head and neck squamous cell carcinoma." (PMID 29221158, 2017). "We also show that inhibition of Mcl-1 indeed renders gastric cancer cells sensitive to Taxol-induced apoptosis." (PMID 29137317, 2017). "We further found that miR-125b is an important tumor suppressor miRNA capable of inhibiting cell proliferation and invasion and promoting cell apoptosis by targeting MCL1 in gastric cancer." (PMID 26504803, 2015). "In our study, MCL1 was further confirmed to be a direct target of miR-125b via luciferase activity assays in gastric cancer cells." (PMID 26504803, 2015). "Meanwhile, previous study reported activation of miR-512-5p by epigenetic treatment induces suppression of Mcl-1, resulting in apoptosis of gastric cancer cells." (PMID 26258591, 2015). "Western blot analysis of miR-125b mimics/MCL1-siRNA-transfected gastric cancer cells indicated a higher expression of cleaved caspase-3 and PARP, which coincide with apoptosis, compared to controls." (PMID 26504803, 2015). "miR-101 and miR-515-5p target Mcl-1, which are downregulated in gastric cancer, lead to increased levels of Mcl-1 and an anti-apoptotic phenotype." (PMID 23629677, 2013).
gastric cancer (continued). "Celecoxib activation of miR-29c induces suppression of the oncogene Mcl-1, a target of miR-29c and apoptosis in gastric cancer cells." (PMID 23629677, 2013). "Hence, suppressing Mcl1 expression has been shown to enhance apoptosis in gastric cancer cells, suggesting that targeting this anti-apoptotic protein is a promising strategy to overcome chemotherapy resistance." (PMID 40765835, 2025). "In contrast, the MCL1 gene was significantly more expressed in both gastric cancer cell lines, which could act as a drug resistance mechanism." (PMID 38972247, 2024). "Specifically, these compounds promote apoptotic bleb formation, as they affect the expression of pro-apoptotic and anti-apoptotic proteins such as Bad, Bax, Mcl-1, and Bcl-2, leading to a delicate balance shift tipping the scales towards apoptosis in gastric cancer cells." (PMID 37958986, 2023). "Our work provides further understanding of CIP2A-GSK3β-MCL-1 regulatory axis in tumorigenesis and may present celastrol as a novel therapy for gastric cancer." (PMID 37470692, 2023). "Additionally, the protein level of phosphor-Janus kinase 2 (JAK2) was diminished by genipin treatment, indicating that the STAT3/JAK2/Mcl-1 pathway is suppressed by genipin treatment in gastric cancer cells." (PMID 35628447, 2022). "Furthermore, Mcl-1 knockdown also induces cell cycle arrest via decreasing cyclin D1, cell division cycle gene 2 (cdc2), and cyclin-dependent kinases 4/6 in gastric cancer." (PMID 35457012, 2022). "The molecules, mcl1 and Bcl-xL, inhibit the proliferation of gastric cancer cells and promote apoptosis and then increase the level of miR-133–3p that regulates the antiapoptotic molecules (Caspase-9 and Bcl-xl) to inhibit cell proliferation and promote apoptosis." (PMID 33763149, 2021). "After down-regulating FBXW7 in the gastric cancer cells, we found that the down-regulation of MCL1 expression induced by LH could be partially restored." (PMID 33126914, 2020). "In our study, we found that the combination of BCL2 and MCL1 inhibitors could induce gastric cancer cells more significantly apoptosis." (PMID 33126914, 2020). "Additionally, the protein level of phospho Janus kinase 2 (JAK2) was decreased by Genipin treatment, indicating that the Stat3/JAK2/Mcl-1 pathway is suppressed by Genipin treatment in gastric cancer cells." (PMID 31351462, 2019). "Additionally, miR-302b, miR-320, and miR-512-5p have been validated to target MCL1 and regulate cancer progression and apoptosis in malignant pleural mesothelioma, cervical cancer, and gastric cancer, respectively." (PMID 29361709, 2018). "Furthermore, inhibition of Mcl-1 or PI3K/Akt pathway significantly reversed the resistant phenotype of Taxol-resistant human gastric cancer cells." (PMID 29137317, 2017). "Furthermore, in human gastric cancer cells AGS, quercetin caused morphological changes and reduced total survival through apoptotic cell death, decreased anti-apoptotic proteins Mcl-1, Bcl-2, and Bcl-x and increased the pro-apoptotic proteins Bad, Bax, and Bid." (PMID 35971151, 2022). "Similarly, MYOSLID could enhance the degree of malignancy by promoting the expression of MCL1 in gastric cancer." (PMID 35846431, 2022). "Besides, the apoptosis of the drug-resistant gastric cancer cell lines could also be induced by down-regulating MCL1 or adding LH." (PMID 33126914, 2020). "In conclusion, we report a novel gastric cancer‐associated lncRNA MYOSLID and first discovered that lncRNA MYOSLID is a carcinogenic lncRNA that promotes cell proliferation and inhibits apoptosis in human GC via the miR‐29c‐3p‐MCL‐1 axis." (PMID 31497917, 2019). "In gastric cancer, ENO1 promotes tumor growth 45 by stabilizing the expression of genes such as SOX9, VEGF-α, GPRC5A, and MCL-1." (PMID 40303285, 2025).
gastric cancer (continued). "Here we studied the expression of emerging prognostic markers SOX9, MCL-1, and SPOCK1 (Testican-1) in a cohort of gastric cancer by immunohistochemistry and investigated how individual biomarkers and their combinations predict disease prognosis." (PMID 35221802, 2022). "Here we present a study on the expression of emerging biomarkers SOX9, MCL-1 and SPOCK1 in a gastric cancer tissue microarray (TMA)." (PMID 35221802, 2022). "The expression of MCL-1 in stomach is regulated by hypoxia-inducible factor 1 alpha (HNF1-α) in Helicobacter pylori-infected human gastric epithelium and HMGB1 in gastric cancer cells." (PMID 35221802, 2022). "We found frequent expression of SPOCK1 (in both nuclei and cytoplasm), MCL-1 and SOX9 in gastric cancer." (PMID 35221802, 2022). "Another study demonstrated the ability of CT to potentiate the antitumor effects of doxorubicin on gastric cancer cells through down regulation of STAT3 target genes such as Bcl-xL, Mcl-1, surviving and XIAP." (PMID 33544704, 2021). "Taken together, in this study, lycorine hydrochloride (LH), an extract of Lycoris radiate, was proved to reduce the accumulation of MCL1 through FBXW7-MCL1 axis and induce apoptosis of gastric cancer cells." (PMID 33126914, 2020). "As the unique pro-survival Bcl-2 family member, Mcl-1 is required for maintaining cell growth and survival of NSCLC, prostate, colorectal, liver, and gastric cancer cells." (PMID 32276600, 2020). "Then, gastric cancer cell lines SGC‐7901 and BGC‐823 were transfected with MCL‐1 siRNA to knockdown their expression, which was confirmed by qRT‐PCR and Western blot." (PMID 31497917, 2019). "Together, these data demonstrate that Mcl-1 is stabilized by the PI3K/Akt pathway, through which Mcl-1 contributes to the acquired resistance of human gastric cancer cells to Taxol." (PMID 29137317, 2017). "Mcl-1 is shown to be stabilized responses to PI3K/Akt pathway hyper-activation, thereby confers resistance to Taxol in human gastric cancer cells." (PMID 29137317, 2017). "While exploring the functional effect of miR-125b and MCL1 on gastric cancer by cell proliferation, we found that upregulation of miR-125b inhibited the proliferation capacity of MGC-803 cells via functional downregulation of MCL1 expression." (PMID 26504803, 2015). "The ectopic expression of miR-101 significantly inhibited cellular proliferation, migration, and invasion of gastric cancer cells by targeting EZH2, Cox-2, Mcl-1, and Fos." (PMID 23768087, 2013). "MYC directs the transcription of MCL-1 directly in gastric cancer cells; however, we did not observe a transcriptional regulation of MCL-1 by MYC." (PMID 38918775, 2024). "Indeed, previous study showed that downregulation of miR-193a enhances Myeloid cell leukemia-1 (MCL1) expression and promotes gastric cancer proliferation, confirming the tumor suppressive role of miR-193a." (PMID 33718136, 2021). "In gastric cancer, the ectopic expression of miR-101 significantly inhibits cell proliferation, migration and invasion by targeting enhancer of zeste homolog 2 (EZH2), Cyclooxygenase-2 (COX-2), Myeloid cell leukemia-1 (MCL-1) and Fos." (PMID 34659567, 2021). "Besides, we unveiled that LH reduced the protein stability of MCL1 by up-regulating ubiquitin E3 ligase FBXW7, arrested cell cycle at S phase and triggered apoptosis of gastric cancer cells." (PMID 33126914, 2020). "Furthermore, the qRT-PCR and western blotting assays showed that the transcriptional and protein levels of MCL1 and BCL2 in BCL2-drug-resistant gastric cancer cell lines were higher than those in normal gastric cancer cell lines." (PMID 33126914, 2020). "Thereby, we concluded that LH could down-regulate the stability of MCL1 through FBXW7, promoting gastric cancer cells apoptosis, and inhibiting cells growth." (PMID 33126914, 2020). "Thus, our study suggests that Genipin is useful as a new therapeutic agent for gastric cancer targeting JAK/Stat3 and Mcl-1." (PMID 31351462, 2019).
gastric cancer (continued). "Moreover, LINC00152, a lncRNA overexpressed in gastric cancer, was proved to sponge MIR193A to increase MCL1 expression thereby promoting cells proliferation." (PMID 31523496, 2019). "In this study, we demonstrated that overexpression of miR-125b upregulated apoptosis-related cleaved caspase-3 and PARP and that downregulating MCL1 could enhance the expression of 5-FU-induced cleaved caspase-3 and PARP in gastric cancer cells." (PMID 26504803, 2015). "To confirm that the IMQ resistance effect of Mcl-1 overexpression was not cell-specific, we generated another Mcl-1-overexpressing clone from the AGS gastric cancer cell line and named it AGS IV." (PMID 39272918, 2024).
non-small cell lung carcinoma (65 papers, 1999 to 2025). A group of at least three distinct histological types of lung cancer, including non-small cell squamous cell carcinoma, adenocarcinoma, and large cell carcinoma. "Parthenolide reduces MCL-1 levels while increasing MAIP-1 levels in non-small cell lung cancer (NSCLC) cells, causing ER stress and inducing cell cycle arrest and apoptosis." (PMID 37047552, 2023). "What is more, MCL1 copy number variations have been reported to be associated with cancer prognosis in papillary thyroid carcinoma and non-small-cell lung carcinoma." (PMID 29152113, 2017). "In one study, increased ER-mitochondrial Ca2+ transfer in non-small cell lung carcinoma cells was caused by MCL1–VDAC interactions that promoted cell migration by increasing mitochondrial ROS production." (PMID 28848710, 2017). "In the osteosarcoma cells we used, S63845 sensitivity correlated with MCL-1 expression, as had been previously noted in non-small cell lung cancer." (PMID 39497108, 2024). "Formononetin inhibits tumor growth by suppression of EGFR-Akt-Mcl-1 axis in non-small cell lung cancer." (PMID 35372052, 2022). "In non-small cell lung cancer, genomic gains in MCL-1 occur with high frequency during tumor evolution, and tumor progression in transgenic mice was delayed with genetic or pharmacological inhibition of MCL-1." (PMID 35008216, 2021). "The non-small cell lung carcinoma (NSCLC) cell line NCI-H23 was highly sensitive to MCL1 siRNA knockdown in agreement with previous findings." (PMID 25289887, 2014). "MCL-1 was also found to be modulated by PI3K/TOR signaling in the setting of mutant epidermal growth factor receptor (EGFR) driven non-small cell lung cancers." (PMID 20657741, 2010). "In DTCs obtained by treating EGFR-mutated non-small cell lung cancer cells (NSCLC) with gefitinib, a significant upregulation of the mTOR-mediated anti-apoptotic protein MCL1 could be found, indicating that DTCs are closely associated with anti-apoptosis." (PMID 37483492, 2023). "In addition, limited single-agent activity of MCL-1 inhibitors can be boosted with rationale combination approaches such as MEK inhibitors in KRAS-mutant non-small-cell lung cancer (NSCLC)." (PMID 33308268, 2020). "In non-small cell lung cancer, cells with high MCL1 levels are more resistant to cisplatin." (PMID 29484127, 2018). "Similarly, MCL1 was found to be increasingly expressed in the side population of non-small cell lung cancer cell lines." (PMID 25749045, 2015). "Moreover, the prognostic significance of high Mcl-1 protein expression has also been demonstrated in breast, ovarian, non-small cell lung cancer and several hematological malignancies." (PMID 25409302, 2014). "In epidermal growth factor receptor (EGFR) mutant non-small cell lung cancer cells, MCL-1 downregulation by a PI3K/mTOR kinase inhibitor in combination with BIM upregulation (a pro-apoptotic member of the bcl-2 family) by a MEK inhibitor has been shown to be critical for the induction of apoptosis." (PMID 22808163, 2012). "Consequently, it is not unexpected that the amplification and overexpression of pro-survival Bcl-2 proteins, such as Bcl-2 and Mcl-1, are found in many cancer types (e.g., non-small-cell lung cancer, breast cancer, ovarian cancer, prostate cancer, and pancreatic cancer)." (PMID 32260280, 2020).
non-small cell lung carcinoma (continued). "Furthermore, miR-101 expression levels have been shown to negatively correlate with MCL1 expression levels in non-small cell lung cancer tissue, and this coupled reduction of miR-101 expression and increase of MCL1 expression are associated with a poorer clinical prognosis." (PMID 29748555, 2018). "Mcl-1 is an antiapoptotic member of the Bcl-2 family frequently upregulated in non-small cell lung carcinoma (NSCLC)." (PMID 25341036, 2014). "In non-small cell lung cancer (NSCLC) cells, Fbxo4 protein levels are reversely correlated with Mcl-1 expression." (PMID 35565262, 2022). "Here, the authors show in non-small cell lung cancer that the anti-apoptotic gene MCL-1 is subject to copy number gains and that deletion of MCL-1 reduces tumour formation." (PMID 32913197, 2020). "These aptamers significantly suppress the growth of human non-small cell lung cancer (NSCLC) tumors in vivo by selectively inhibiting the activation of Stat3 and its downstream proteins such as Bcl-2, Bcl-xL, Mcl-1, survivin, VEGF, Cyclin D1, and c-myc." (PMID 31640176, 2019). "Knockdown of MCL-1 by siRNA or inhibition of MCL-1 by specific pharmacologic inhibitor EU-5148, sensitizes TWEAK-treated non-small cell lung cancer cells to cisplatin-mediated apoptosis." (PMID 28659182, 2017). "Here, using a DNA barcoding approach, the authors demonstrate EGFR TKI treatment in non-small cell lung cancer enriches for resistant subpopulation which can be prevented by treatment with the multikinase inhibitor sorafenib via inhibition of MKNK, STAT3 and MCL1." (PMID 40846697, 2025). "Conversely, not all instances of resistance were attributed to Mcl1 expression, as reported for cisplatin-treated non-small cell lung cancer cells (NSCLC), which induced cell death independently of Mcl1 expression levels." (PMID 34753495, 2021). "MCL1 is one of the most frequently amplified genes in cancer, including a subset of non-small cell lung carcinoma (NSCLC), which may confer dependence on high MCL1 levels for survival." (PMID 30635584, 2019). "Cancer cell models commonly harbour constitutively expressed BAK and multiple PBPs (these may include BCL-2, BCL-XL, MCL-1, A1 and BCL-W coexpression in the case of non-small cell lung cancer – data unshown)." (PMID 18725943, 2008). "Similarly, high Mcl-1 expression promoted cell migration but not proliferation in non-small cell lung cancer (NSCLC) cells and knockdown of Mcl-1 in this cell line inhibited cell migration in scratch wound-healing assays." (PMID 28495532, 2018). "Silencing MCL1 (but not BCL2L1 (bcl-xL)) induced cell death in a subset of triple negative breast cancer (TNBC) and non-small cell lung cancer (NSCLC) cell lines and was correlated with the expression of the various BCL2 family members." (PMID 32645016, 2020).